PDCD4 (programmed cell death 4)
Diseases named in the same sentence as PDCD4 in open-access papers (continued):
Sharing a sentence is not in itself a finding about the gene and the disease.
gastric cancer (continued). "Finally, we showed that miR-23a/b significantly suppressed PDCD4 expression and enhanced tumor growth in a gastric cancer xenograft mouse model." (PMID 28981115, 2017). "PDCD4, as a potent tumor suppressor, may serve as a potential new therapeutic target for gastric cancer, but technical limitations make it difficult to stably express PDCD4 in vivo." (PMID 28981115, 2017). "Interestingly, we identified a discordance between PDCD4 protein and mRNA levels in human gastric cancer tissues." (PMID 27021515, 2016). "In this study, we showed that silencing PDCD4 expression using siRNA could suppress cell apoptosis in gastric cancer cells, whereas overexpressing PDCD4 produced an opposite effect." (PMID 27634902, 2016). "Moreover, we showed that miR-93 inhibited PDCD4 expression and consequently inhibited apoptosis in cultured gastric cancer cells." (PMID 27021515, 2016). "Because miRNAs are generally thought to have expression patterns that are opposite to that of their targets, we investigated whether miR-208a-3p expression was inversely correlated with PDCD4 expression in gastric cancer." (PMID 27634902, 2016). "Interestingly, we observed that the restoration of PDCD4 expression successfully attenuates the anti-apoptotic effects of miR-93 on gastric cancer cells, although miR-93 has many other targets." (PMID 27021515, 2016). "PDCD4 plays a pivotal role in the occurrence and development of gastric cancer." (PMID 27021515, 2016). "We demonstrated that miR-208a-3p suppressed apoptosis in gastric cancer cells by targeting PDCD4." (PMID 27634902, 2016). "In addition, after overexpressing or knocking down miR-93 in gastric cancer cells, we experimentally validated the direct inhibition of PDCD4 translation through miR-93." (PMID 27021515, 2016). "In the present study, we observed that silencing PDCD4 expression through siRNA inhibits apoptosis in gastric cancer cells, whereas overexpressing PDCD4 induced the opposite effects, validating a role for this protein as an essential anti-oncogene during gastric tumorigenesis." (PMID 27021515, 2016). "CagA also promoted mobility of gastric cancer cells by regulating PDCD4." (PMID 25144746, 2014). "However, E-cadherin and PDCD4 decreased in the process of epithelial-mesenchymal transition in gastric cancer." (PMID 25144746, 2014). "Resveratrol also downregulated miR-21 and upregulated PDCD4 in AGS gastric cancer cells." (PMID 25254214, 2014). "Circumstantial evidence supporting this hypothesis includes the observations that inflammation can lead to down-regulation of PDCD4 in colorectal tissue and that miR-21 upregulation in gastric cancer is due to PGE2 induced activation of NF-kB." (PMID 25310697, 2014). "So, PDCD4 interacts with the DNA binding domain of Twist1 and inhibits its DNA binding ability to target genes in human prostate cancer cells.Therefore, we further tested whether PDCD4 could regulate TWIST1 in gastric cancer cells." (PMID 25144746, 2014). "A reduced expression of PDCD4 and overexpression of miR-21 were found in gastric cancer specimens." (PMID 25254214, 2014). "Future research involving mouse models may lead to a better understanding of the role of PDCD4 in the H. pylori-induced EMT of gastric cancer." (PMID 25144746, 2014). "Finally, for gastric cancer, miR-23b promotes tumor development by targeting PDCD4." (PMID 34777498, 2021). "Furthermore, because miR-23a/b and PDCD4 had opposing effects on cell apoptosis, it is quite possible that miR-23a/b suppressed PDCD4 expression and consequently inhibited cell apoptosis and promoted tumor growth during gastric cancer progression." (PMID 28981115, 2017). "Interestingly, it has been reported that cumulative survival rate of gastric cancer patients with PDCD4 expression was significantly higher compared to the patients without PDCD4 expression, impling PDCD4 as a promising target for future anticancer therapies in gastric cancer." (PMID 27634902, 2016).
gastric cancer (continued). "Therefore, modulation of PDCD4 by miR-208a-3p and miR-21 might explain, at least in part, why the upregulation of miR-208a-3p and miR-21 during tumorigenesis can silence PDCD4 and promote tumor cell growth and gastric cancer formation." (PMID 27634902, 2016). "We next investigated whether miR-93 was inversely correlated with PDCD4 in gastric cancer." (PMID 27021515, 2016). "Thus, PDCD4 was regarded as a miR-208a-3p target based on both computational predictions and the inverse correlation between miR-208a-3p levels and PDCD4 protein levels in human gastric cancer." (PMID 27634902, 2016). "Previous findings have indicated that PDCD4 participates in tumorigenesis through the regulation of apoptosis, but the molecular basis of this process has not been fully elucidated, and no studies have shown the upstream regulation of this gene in gastric cancer." (PMID 27021515, 2016). "Likewise, after measuring the PDCD4 protein levels in 16 pairs of gastric cancer tissues and adjacent noncancerous tissues by western blotting, the PDCD4 protein levels were consistently shown to be lower in the gastric cancer tissues." (PMID 27634902, 2016). "KDM2A expression was found to be increased in gastric cancer tissues, and KDM2A may regulate the growth and motility of gastric cancer cells by down-regulating the expression of tumor suppressor programmed cell death 4 (PDCD4) in the progression of gastric cancer." (PMID 26430963, 2015). "However, whether PDCD4 is involved in the EMT induced by CagA in gastric cancer and the specific mechanism still need further elucidation." (PMID 25144746, 2014). "Taken together, our findings demonstrated that circSNTB2 plays an essential role in gastric cancer by regulating miR-6938-5p through G0S2 and PDCD4 genes." (PMID 36366842, 2023). "Future studies should further explore the functional role of the miR-21/PDCD4 axis in gastric cancer, for example by generating PDCD4 CRISPR knockout cell lines or by genetically deleting Pdcd4 in the Gp130F/F mouse model." (PMID 35053428, 2022). "In gastric cancer, miR-93 negatively regulates the tumor suppressor gene Programmed cell death 4 (PDCD4), thereby promoting the development of gastric cancer." (PMID 35306579, 2022). "Interestingly, we showed that the restoration of PDCD4 expression successfully attenuated the anti-apoptotic effects of miR-23a/b on gastric cancer cells, indicating that the targeting of PDCD4 may be a major mechanism through which miR-23a/b exerted its anti-apoptotic function." (PMID 28981115, 2017). "However, the mechanisms underlying PDCD4 function in gastric cancer cells were not clear." (PMID 25144746, 2014). "In gastric cancer cells cocultured with CagA expression plasmid, CagA activated TWIST1 and vimentin expression, and inhibited E-cadherin expression by downregulating PDCD4." (PMID 25144746, 2014). "Immunohistochemistry and statistical analysis demonstrated the relevance of PDCD4 and TWIST1 existed in gastric carcinoma." (PMID 25144746, 2014). "By performing experiments in a gastric cancer xenograft mouse model and gastric cancer cells MKN-45 and AGS, results can identify that miR-23b could target programmed cell death (PDCD4) and promote tumor growth." (PMID 34777498, 2021). "Mechanism studies have shown that HOXD-AS1 epigenetically inhibits PDCD4 expression by binding to the histone methyltransferase enhancer of zeste homologue 2 (EZH2) on the promoter of PDCD4, thus increasing H3K27me3 level and inducing DDP resistance in gastric cancer cells." (PMID 32460771, 2020). "To investigate if miR-23a/b may regulate the apoptosis of gastric cancer cells through a PDCD4-dependent manner, we co-transfected MKN cells with miR-23a/b mimics and PDCD4-overexpression plasmid." (PMID 28981115, 2017). "In this study, we detected an inverse correlation between miR-208a-3p levels and PDCD4 protein levels in human gastric cancer tissues and paired noncancerous tissues." (PMID 27634902, 2016).
gastric cancer (continued). "Moreover, we observed the inverse correlation between miR-93 and PDCD4 protein levels, but not mRNA levels, in human gastric cancer tissues." (PMID 27021515, 2016). "In Gastric Cancer (GC), its upregulation may lead to the suppression of tumor-suppressor genes, including PTEN, RECK, and PDCD4, and promote proliferation, migration, and apoptosis inhibition." (PMID 32258003, 2020).
ovarian carcinoma (32 papers, 2009 to 2025). A malignant neoplasm originating from the surface ovarian epithelium. "PDCD4, an important tumor suppressor, was revealed to be associated with the malignant phenotype of ovarian cancer." (PMID 32934709, 2020). "Our present study identified Pdcd4 as an ovarian cancer associated gene based on its differential expression patterns between normal and malignant ovarian samples." (PMID 19728867, 2009). "Higher Pdcd4 expressions were associated with better disease free survival of ovarian cancer patients." (PMID 19728867, 2009). "In another study, berberine increased the expression of programmed cell death-4 (PDCD4) by inhibiting the expression of miR-21, a known molecule associated with ovarian cancer cisplatin resistance, thereby increasing apoptosis and enhancing cisplatin sensitivity." (PMID 32934709, 2020). "Importantly, staining for PDCD4 demonstrated a loss of expression which is similar to the profile observed in lung, colon, prostate, and ovarian cancers." (PMID 26867589, 2016). "The loss or reduction of PDCD4 expression may be a reason for chemoresistance in ovarian cancer, and the restoration of PDCD4 expression may reverse the resistance of ovarian cancer to chemotherapy." (PMID 24348845, 2014). "In addition, a consistent decrease in PDCD4 expression levels was associated with the steps from normal to borderline to malignant ovarian tissues, and PDCD4 over-expression in ovarian cancer cells resulted in malignant growth inhibition." (PMID 20831814, 2010). "Nonetheless, our study indicated that the loss of Pdcd4 was a common abnormality at molecular level in ovarian cancer and it could be a potential prognostic marker in ovarian cancer patients." (PMID 19728867, 2009). "Our study demonstrated that the loss of Pdcd4 was a common abnormality at molecular level in ovarian cancer and it might be a potential prognostic factor in ovarian cancer patients." (PMID 19728867, 2009). "Therefore, we also tested whether there was an association between Pdcd4 expression and platinum sensitivity of ovarian cancer." (PMID 19728867, 2009). "The association between PDCD4 (programmed cell death 4) protein expression level and miR-106a upregulation in the ovarian cancer OVCAR3 cell line and the cisplatin (DDP)-resistant ovarian cancer OVCAR3/CIS cell line was studied using stem-loop qPCR." (PMID 37627777, 2023). "Subsequently, PDCD4 was found to inhibit the malignant phenotype in ovarian cancer cells and suppress malignant metastasis, with loss of the protein associated with increased invasion." (PMID 35847932, 2022). "Berberine increases cell sensitivity to cisplatin through the miR-21/PDCD4 axis, by decreasing miR-21 expression and function by enhancing the levels of its target PDCD4, an important tumor suppressor of ovarian cancer." (PMID 35046810, 2021). "In summary, the present study demonstrated that the enhancement of miR-106a expression contributes to the generation of CDDP-resistant ovarian cancer cells, partly by targeting PDCD4." (PMID 24348845, 2014). "The central role of PDCD4 in ovarian cancer is further supported by observations that lower levels of this tumor suppressor correlate directly with poor prognosis of ovarian cancer patients." (PMID 24865582, 2014). "Another oncogenic miRNA in ovarian cancer is miRNA-182, which has been shown to promote cell growth, invasion and chemoresistance by targeting programmed cell death 4 (PDCD4) and was able to reduce chemosensitivity of ovarian cancer cells to Taxol." (PMID 23591839, 2013). "The Akt pathway was also shown to mediate serum-induced proteasomal degradation of PDCD4 in ovarian cancer." (PMID 23272133, 2012). "The objective of the current study was to further investigate the function and modulation of PDCD4 in ovarian cancer cells." (PMID 22272332, 2012). "Firstly, wound healing assay was used to monitor the time required for the closing of the wound in control and PDCD4 over-expressing ovarian cancer cells." (PMID 22272332, 2012).
ovarian carcinoma (continued). "The PI3K-Akt pathway was implied to be involved in the regulation of PDCD4 degradation in ovarian cancer cells." (PMID 22272332, 2012). "In the current study, ectopic PDCD4 expression induced cell cycle arrest at G1 stage and consequently suppressed ovarian cancer cell proliferation." (PMID 22272332, 2012). "According to our previous findings, a differential localization of PDCD4 was observed between normal and malignant ovarian tissue samples: more cytoplasmic localization of PDCD4 was observed in ovarian cancer tissue samples." (PMID 22272332, 2012). "Our results were in concordance to these findings and implied the involvement of p-Akt pathway in the regulation of PDCD4 in ovarian cancer cells." (PMID 22272332, 2012). "To further investigate the role of PDCD4 in ovarian cancer, in the current study, we examined the potential tumour suppressor functions of PDCD4 in ovarian cancer cells, and the plausible mechanism that regulates PDCD4." (PMID 22272332, 2012). "To explore the underlying mechanisms for the inhibitory effects of PDCD4 on ovarian cancer cell proliferation, we assessed the effect of PDCD4 on cell cycle progression using flow cytometry analysis." (PMID 22272332, 2012). "Our results indicated that the depletion of PDCD4 after the re-addition of serum in ovarian cancer cells was due to the proteasome-mediated degradation." (PMID 22272332, 2012). "Predominant nuclear localization of Pdcd4 was found in normal ovarian tissues while ovarian carcinomas showed mainly cytoplasmic localization of Pdcd4." (PMID 19728867, 2009). "The aim of this study was to investigate the expression, prognostic significance and potential function of Pdcd4 in ovarian cancer." (PMID 19728867, 2009). "They applied semi-quantitative PCR to measure Pdcd4 mRNA expression in serous subtype of ovarian cancer tissues." (PMID 19728867, 2009). "Moreover, PDCD4 overexpression enhances the sensitivity of ovarian cancer cells to cisplatin by activating the death receptor pathway." (PMID 32260415, 2020). "In ovarian cancer, lower PDCD4 expression correlates with shorter disease-free survival (DFS)." (PMID 32260415, 2020). "Furthermore, it has been found that miR-182 plays oncogenic roles by directly targeting and negatively regulating PDCD4 in ovarian cancer." (PMID 31703725, 2019). "Furthermore, miR-182-5p was also identified as playing a key role in the development of chemoresistance in ovarian carcinomas due to its gene-regulating capacity on programmed cell death 4 (PDCD4)." (PMID 28273813, 2017). "Moreover, miR-106a modulates cisplatin sensitivity through regulation of PDCD4 (programmed cell death 4) in ovarian cancer cells." (PMID 25760076, 2015). "However, in solid tumors including ovarian cancer, the tumor suppressor gene programmed cell death 4 (PDCD4) appears to be one of the most important functional miR-21 targets." (PMID 24865582, 2014). "Furthermore, inhibition of miR-21 with a miR-21 specific oligonucleotide inhibitor (antagomiR) increased the PDCD4 protein levels, which confirmed previous results that miR-21 regulates PDCD4 in ovarian cancer cells." (PMID 24865582, 2014). "The PDCD4 effect appears to be specific for cisplatin-induced apoptosis in ovarian cancer cells." (PMID 24194922, 2013). "The investigations on the role of PDCD4 in ovarian cancer carcinogenesis were rather limited." (PMID 22272332, 2012). "PDCD4 also has effect on ovarian cancer cell invasion demonstrated by transwell invasion assay." (PMID 22272332, 2012). "Our previous immunohistochemistry study showed a differential cellular localization pattern of PDCD4 between normal and malignant ovarian cells, suggesting that PDCD4 might translocate from the nucleus to the cytoplasm during ovarian cancer development." (PMID 22272332, 2012). "We then investigated the endogenous PDCD4 localization in ovarian cancer cells." (PMID 22272332, 2012).
ovarian carcinoma (continued). "Besides proliferation, we also demonstrated the inhibitory effects of PDCD4 on ovarian cancer cell migration and invasion." (PMID 22272332, 2012). "We speculated that the accumulation of Pdcd4 in the nucleus might negatively regulate cell proliferation while the cytoplasmic sequestration of Pdcd4 might abolish its function in ovarian cancer cells." (PMID 19728867, 2009). "Our results suggested that Pdcd4 might translocate from the nucleus to the cytoplasm during ovarian cancer development." (PMID 19728867, 2009). "Among ovarian cancer patients with known recurrence status (n = 79), by categorizing Pdcd4 expressions into two levels at median value (ie, lower expression <= 0.28, higher expression > 0.28), Pdcd4 was found to be significantly associated with disease-free survival (log rank = 4.355, p = 0.037)." (PMID 19728867, 2009). "As it has been suggested that the role of Pdcd4 might be cell type specific, the regulatory mechanisms of Pdcd4 in ovarian cancer cells still remains to be investigated." (PMID 19728867, 2009). "Programmed cell death 4 (PCDC4), a tumor suppressor gene reduced in many cancer types—including ovarian cancer —was also reduced upon RBPMS knockout." (PMID 35008958, 2022). "Previous studies in AML, endometrial and ovarian cancer, showed an inhibition of PI3K/AKT which led to subsequent upregulation of PDCD4 and concomitant upregulation of cell cycle inhibitor, p27." (PMID 34359600, 2021). "Overall, these observations suggest that ILK regulates the JNK/c-JUN pathway in cisplatin-resistant ovarian cancer via modulation of DUSP8, MARVELD3, PDCD4, MAPK8IP1, MAPK8IP2, and HIPK3." (PMID 32260415, 2020). "Two different studies found that miR-182 overexpression, by negatively regulating programmed cell death 4 (PDCD4), was involved in chemoresistance exacerbation of lung and ovarian cancers to cisplatin and paclitaxel, respectively." (PMID 30211115, 2018). "Two ovarian cancer cell lines, OV2008 and C13, have high expression level of the endogenous PDCD4, which was found localized exclusively in the nucleus under normal culture condition." (PMID 22272332, 2012). "miR-106a may be involved in the development of drug resistance and the regulation of PDCD4 expression, at least in part, by modulating CDDP-induced apoptosis in ovarian cancer cells." (PMID 24348845, 2014). "As noted from our results, the magnitude of suppression of ovarian cancer cell proliferation, migration and invasion was not in proportion to the over-expression levels of PDCD4 protein in those stable clones." (PMID 22272332, 2012). "One PDCD4 over-expressing stable clone SKOV3-PDCD4, was established in ovarian cancer cell SKOV3." (PMID 22272332, 2012). "The physiological roles of Pdcd4 in human cancers are still poorly understood and its role in ovarian cancer has not been thoroughly investigated." (PMID 19728867, 2009). "The flow cytometry analysis indicated that over-expression of PDCD4 induced cell cycle arrest mainly at G1 stage; 1.2 (p< = 0.01) and 1.8 (p<0.01) fold increase in the percentage of the cells at G1 stage in OVCA433-PDCD4 and SKOV3-PDCD4 ovarian cancer cells, respectively (p< = 0.01)." (PMID 22272332, 2012). "Our results indicated that p-Akt but not p-ERK was required for the degradation of PDCD4 upon serum stimulation, and thus PI3K-Akt pathway might play a direct role on the modulation of PDCD4 degradation in ovarian cancer cells." (PMID 22272332, 2012).